LEP (leptin)
Diseases named in the same sentence as LEP in open-access papers (continued):
Sharing a sentence is not in itself a finding about the gene and the disease.
Obesity (continued). "As one of the hormones directly connected to body fat and obesity, leptin, a hormone released from the fat cells in adipose tissue, sends signals to the hypothalamus in the brain." (PMID 40283801, 2025). "Increasing evidence suggests that the pathophysiology of obesity involves neuroinflammation, hypothalamic dysfunction, and significant endocrine dysfunction, including the regulation of leptin (LEP), ghrelin, insulin, and reproductive hormones." (PMID 41226484, 2025). "Adipokines, in particular, elevated leptin levels, are associated with inflammatory processes through the release of pro-inflammatory cytokines, which are involved in both MIG attacks and obesity." (PMID 41470814, 2025). "In obesity, the adipokine profile shifts towards increased pro-inflammatory factors, such as leptin, and decreased anti-inflammatory factors, such as adiponectin." (PMID 40842998, 2025). "The identification of leptin is the most significant discovery in obesity research, as it has helped unravel the architecture of neuroendocrine circuits that control appetite and energy homeostasis." (PMID 40282897, 2025). "Measurements taken before and after the intervention showed significant improvements in anthropometry, body composition, and obesity-related biomarkers (leptin, ALT, AST)." (PMID 40549339, 2025). "Leptin, which is notoriously abundant in obesity, triggers the expression of a host of pro-inflammatory and pro-tumorigenic cytokines, notably IL-1, IL-6, and TNF-α within macrophages." (PMID 40040878, 2025). "Fortunately, leptin supplementation has been shown to reverse obesity and improve metabolism in children with congenital leptin deficiency." (PMID 39812542, 2025). "The anti-obesity effects of gallic acid are attributed to its ability to inhibit leptin secretion, reduce triglycerides, LDL, and VLDL levels, while simultaneously increasing HDL levels." (PMID 40807278, 2025). "These associations were most pronounced in non-obese females, in line with earlier findings of possible sex-hormone modulation and that obesity-related central leptin resistance impairs its beneficial effects." (PMID 41516046, 2025). "Leptin, an adipocyte-derived hormone, plays a role in appetite regulation and energy expenditure but is often elevated in individuals with obesity, leading to leptin resistance." (PMID 40863890, 2025). "Conversely, mice with either the global or neuron-specific deletion of PTP1B exhibit a lean phenotype, heightened sensitivity to leptin, and resistance to diet-induced obesity." (PMID 39941054, 2025). "Leptin stimulates the POMC neuron, causing release of α-MSH, which acts on MC4R, increasing satiety and reducing obesity." (PMID 41002740, 2025). "Meanwhile, certain Lactobacillus species are known for their anti-obesity properties that rely on their ability to decrease leptin levels and regulate lipid metabolism." (PMID 40917104, 2025). "Leptin, another dysregulated adipokine, tends to increase (hyperleptinemia) resulting from central leptin resistance, which is related to obesity, insulin resistance, and inflammation in both GDM and T2D." (PMID 41374008, 2025). "Beyond the well-established adipokines like adiponectin and leptin, resistin and visfatin have also come to the forefront in recent studies on obesity and cancer." (PMID 40040878, 2025). "Metabolic and vascular dysfunction of obesity, including inflammation, IR and leptin resistance, have been considered as the key risks to depression and anxiety development." (PMID 40278960, 2025). "Crucially, the study positions OB EVs and their leptin content as central players linking obesity to breast cancer progression." (PMID 40485730, 2025). "A longer high-fat diet would lead to significant obesity, as well as leptin resistance, which we aimed to avoid in this study." (PMID 40018036, 2025).
Obesity (continued). "Chronic hyperleptinemia, often observed in obesity, results in “selective leptin resistance”, where its appetite-suppressing effects wane while its vascular effects persist." (PMID 40430185, 2025). "Obesity leads to adipose tissue expansion through hypertrophy and hyperplasia, accompanied by increased levels of leptin." (PMID 41155389, 2025). "Obesity, satiety, glucocorticoids, insulin, and acute infection increase leptin levels, whereas cold stimulation, fasting, and testosterone decrease leptin levels." (PMID 39812542, 2025). "Elevated leptin levels in obesity, coupled with reduced adiponectin levels in individuals with increased adipose tissue mass, correlate with an elevated cardiovascular risk." (PMID 40310144, 2025). "In obesity, leptin signaling is commonly impaired (leptin resistance), while adiponectin levels are reduced." (PMID 41374016, 2025). "Circulating leptin levels are positively correlated with body fat percentage, showing elevated concentrations in obesity and reduced levels in cachexia or anorexia." (PMID 41302083, 2025). "Flaxseed polysaccharide, by activating the AMPK signaling pathway, accelerates the process of lipid metabolism, eliminating leptin resistance and improving anti-obesity efficacy." (PMID 40428495, 2025). "Research has shown that individuals with obesity often display lower concentrations of growth hormone–releasing peptides while having higher levels of leptin." (PMID 40901291, 2025). "FIP-fve reduced body weight, blood lipids, glucose, and crucial cytokines, including leptin and resistin, which are central to obesity-related insulin resistance and metabolic diseases." (PMID 40998975, 2025). "In obesity, elevated leptin has also been reported to induce osteoblastic differentiation of calcifying VSMC via ERK phosphorylation and PI3K/AKT activation, upregulating the RANKL-BMP4 axis." (PMID 40940776, 2025). "For example, elevated leptin levels in obesity accelerate skeletal and dental development, while pro-inflammatory adipokines further exacerbate these changes." (PMID 40150659, 2025). "In this study, the authors treated primary differentiated adipocytes with various factors known to increase white adipose tissue concomitant with obesity and demonstrated that only leptin suppressed TET2 expression." (PMID 40620794, 2025). "TRZ also induces adiponectin expression, and TRZ regulates leptin sensitivity in T2D patients with obesity." (PMID 40498212, 2025). "Obesity exacerbates migraine severity through chronic inflammation and the dysregulation of adipocytokines like leptin and adiponectin." (PMID 39861467, 2025). "Along with dedicating to identifying the natural ligands of numerous orphan GPCRs, extensive studies show the pathophysiology of orphan GPCRs in obesity and their interaction with leptin signaling." (PMID 41016636, 2025). "The results demonstrate that HE NPs improve metabolic dysfunction and OSA in obesity by reducing ER stress and restoring leptin sensitivity, offering a novel therapeutic strategy." (PMID 40923443, 2025). "Leptin, an adipocyte-derived hormone, plays a crucial role in signaling satiety and regulating energy expenditure; however, in obesity, leptin resistance impairs these feedback mechanisms, leading to persistent hunger and a reduced metabolic rate." (PMID 39997062, 2025). "Leptin analogues are currently used off-label for obesity treatment in patients with hypoleptinism due to congenital leptin deficiency (CLD)." (PMID 39929239, 2025). "In a diet‐induced obesity model, increased body mass and adiposity, increased leptin levels (hyperleptinemia), and reduced plasma follicle‐stimulating hormone (FSH) and testosterone were observed." (PMID 40195898, 2025). "Adipokine production, i.e., leptin, adiponectin, resistin and visfatin, is a key mechanism through which obesity leads to a pro‐inflammatory state." (PMID 39152660, 2025).
Obesity (continued). "Leptin is a key adipokine involved in the regulation of energy intake and expenditure, playing a crucial role in obesity and insulin resistance." (PMID 40630340, 2025). "Studies have shown that in patients with obesity, adipocytes secrete estrogen, leptin, and inflammatory factors that regulate the expression of PD‐1 on the surface of macrophages and CD8‐positive T cells, thereby promoting responsiveness to immunotherapy." (PMID 41245885, 2025). "In patients with obesity, elevated circulating leptin levels can result in excessive stimulation of leptin receptors, leading to receptor desensitization and impaired signaling, contributing to the dysregulation of energy balance seen in obesity." (PMID 40500780, 2025). "Obesity and immunometabolic depression also share metabolic disturbances (e.g., increased leptin and insulin and reduced adiponectin)." (PMID 41375608, 2025). "All these findings suggest that leptin is a potential biomarker of hepatic fibrosis in patients with obesity." (PMID 40507178, 2025). "Plasma leptin levels were significantly elevated in patients with severe obesity and correlated closely with body mass index and waist circumference." (PMID 40943431, 2025). "Leptin resistance is a common phenomenon in obesity that renders the metabolic actions of leptin ineffective, even with high doses of exogenous leptin." (PMID 41251447, 2025). "Previous studies have provided valuable insights into the role of leptin and ghrelin receptor mRNA in the hypothalamus and their involvement in the pathophysiology of obesity." (PMID 40087612, 2025). "The notion that MC4R is downstream of leptin targets is supported by the effectiveness of MC4R agonism to reduce hyperphagia and obesity in leptin-deficient individuals." (PMID 41251447, 2025). "The second one, as a consequence of a chronic inflammation in obesity, driven by excessive release of pro-inflammatory cytokines, diminishes receptor sensitivity and disrupts downstream signaling cascades, reducing leptin efficacy." (PMID 39857741, 2025). "For instance, research has shown that leptin resistance, which is characterized by reduced responsiveness to leptin, is a common feature of obesity." (PMID 40087612, 2025). "Any disruption in ligands or receptors involved in melanocortin signaling, such as rare, pathogenic mutations in LEP, LEPR, or MC4R encoding melanocortin 4 receptor, lead to early-onset severe obesity." (PMID 39237720, 2025). "Obesity frequently results in leptin resistance, marked by increased blood leptin concentrations and diminished responsiveness, especially in the hypothalamus, which is essential for energy regulation." (PMID 40989799, 2025). "Hesperidin nanoparticles (HE NPs) effectively combat obesity and sleep‐disordered breathing in mice by enhancing leptin sensitivity." (PMID 40923443, 2025). "There are many obesity-related hormones; however, only the key hormones, insulin, leptin, and adiponectin, were measured." (PMID 40431382, 2025). "Leptin also seems to contribute to obesity in women with polycystic ovary syndrome or uterine fibroids." (PMID 40191968, 2025). "Adiponectin levels typically decrease, whereas leptin levels increase in obesity, insulin resistance, type-2 diabetes, and metabolic syndrome, ultimately leading to increased cardiovascular risk." (PMID 39940942, 2025). "Leptin, a key adipokine secreted by adipose tissue (AT), has emerged as a critical mediator linking obesity and breast cancer, both of which are major global health concerns." (PMID 40485730, 2025). "Studies in rats with diet-induced obesity suggest that the complex of fucoxanthin and CLA can lower serum triacylglycerol, glucose, and leptin levels and exhibit anti-obesity effects." (PMID 40699855, 2025). "Leptin resistance is one of the key features driving the pathogenesis of obesity and obesity-related inflammatory disorders." (PMID 40725425, 2025).
Obesity (continued). "Circulating leptin levels positively correlate with BP in obesity, and leptin can increase BP via SNS activation." (PMID 40761303, 2025). "This study reinforces the understanding that the ghrelin–leptin hormonal axis plays a central role in the pathophysiology of obesity and in the metabolic response following metabolic and bariatric surgery." (PMID 41441006, 2025). "For example, polymorphisms in the FTO, MC4R, LEP, and LEPR genes have been significantly associated with obesity and hypertriglyceridemia in Mexican children aged 4–13 years (n = 718)." (PMID 40647298, 2025). "The active free form of circulating leptin in individuals with obesity accounts for 85% of total leptin, inducing long-form leptin receptor (LepRb) desensitization through chronic overstimulation." (PMID 40278960, 2025). "For instance, with regard to obesity, researchers have reported that a sustained high-fat diet (HFD) and leptin deficiency impact neurogenesis in the ARC." (PMID 41303399, 2025). "Conversely, the deletion of SOCS3 in hypothalamic neurons has demonstrated improvements in leptin sensitivity, a reduction in appetite, and protection against diet-induced obesity." (PMID 40283443, 2025). "In obesity, the dysregulated secretion of adipokines such as leptin, adiponectin, resistin, and chemerin from AT affects periodontal tissues through multiple pathways." (PMID 41246338, 2025). "For instance, a study involving 141 Korean women found higher leptin levels among individuals with obesity and a positive correlation between leptin and waist circumference." (PMID 41439942, 2025). "We observed an increase in the expression of genes encoding CCL2, LEP, and the demethylase KDM6B in vWAT of patients with class II to III obesity, compared to the normal weight/overweight group." (PMID 40518865, 2025). "In obesity, leptin dysregulation impairs not only gonadotropin-releasing hormone (GnRH) secretion but also the production of fertility-related hormones, potentially leading to infertility." (PMID 40002424, 2025). "Considering the metabolic abnormalities of obesity (leptin resistance and hypoadiponectinemia) that accentuate both inflammation and oxidative damage, mitochondrial dysfunction can be considered a central point in the biology of immunometabolic depression." (PMID 41375608, 2025). "After adjustment for potential confounders, women with obesity had a 63% higher probability of presenting altered serum leptin levels (PR = 1.63; 95% CI: 1.32–2.02; p < 0.001) compared with those without obesity." (PMID 41439942, 2025). "Leptin, a hormone primarily produced by adipose tissue, regulates energy balance and appetite, while contributing significantly to obesity and cancer progression." (PMID 40565190, 2025). "The conflicting effect of vitamin D supplementation on leptin can be partly attributed to the variability of leptin in obesity, depending on the stage of weight change." (PMID 41384023, 2025). "Taken together, these findings suggest that leptin is involved in the pathogenesis of obesity-related asthma." (PMID 40083433, 2025). "Anti-obesity of probiotics is related to improvements in lipid metabolism, insulin sensitivity, anti-inflammation, or control of intestinal hormones like leptin or GLP-1, which is frequently accompanied by modulating the intestinal microbiota." (PMID 40218949, 2025). "Elevated leptin levels in subjects affected with obesity further exacerbate bone fragility by negatively correlating with OPG and increasing radial cortical porosity and tibial trabecular thickness." (PMID 39940349, 2025). "The consistent findings from animal and human studies underscore the potential of SHE to modulate leptin levels and promote metabolic balance, positioning it as a promising natural option for obesity management." (PMID 40535914, 2025). "Mice lacking SOCS3 in the brain or specifically in POMC neurons exhibit enhanced leptin sensitivity and are resistant to diet-induced obesity." (PMID 41516046, 2025).
Obesity (continued). "In moderate- to high-leptin conditions, similar to obesity, leptin regulates ovarian steroidogenesis." (PMID 40725447, 2025). "These DRNVglut3 neurons have been identified as downstream targets of leptin signaling and represent a potential therapeutic target for obesity." (PMID 41016636, 2025). "Particularly, leptin, resistin, and PCSK9 demonstrated obvious decreases compared to the Fat only group, indicating FIP-fve’s ability to ameliorate obesity-associated metabolic and inflammatory alterations." (PMID 40998975, 2025). "Maintains mucosal integrity, regulates local and systemic immunity, reduces obesity, stimulates leptin synthesis, releases anorexigenic hormones." (PMID 41244044, 2025). "In our study, we observed a significant increase in serum leptin levels in rats with obesity models." (PMID 40900465, 2025). "While the relationship between sleep and obesity phenotype is still unclear, the evidence shows that chronic lack of sleep results in weight gain through endocrine pathways including leptin and ghrelin which regulate appetite." (PMID 40027500, 2025). "Leptin, which is elevated in obesity, has pro-inflammatory effects and can exacerbate pancreatic injury." (PMID 40937420, 2025). "Obesity has a negative impact on lipid profile and glycemic control in type 2 diabetes patients, which highlights the significance of considering the effect of obesity on the relationship between leptin and lipid profile in diabetic patients." (PMID 41239622, 2025). "Elevated leptin levels are detected in the circulation and in extracellular vesicles (EVs) released by adipose tissue, particularly in cases of obesity." (PMID 40485730, 2025). "This review demonstrates that yoga can effectively regulate adipocytokines such as leptin and adiponectin, suggesting potential anti-obesity effects and improvement in obesity-related chronic inflammation." (PMID 39897330, 2025). "Concentrations of adipokines have been assessed in ovarian follicular fluid, and levels of TNF-α, leptin, IL-18, and IL-10 appear to be correlated with BMI, suggesting follicular fluid-specific effects of obesity." (PMID 40755647, 2025). "The weak positive correlation for leptin suggests that higher maternal adiposity—as reflected by a thicker abdominal wall—is associated with higher leptin levels, a finding that aligns with the established understanding of leptin physiology in obesity." (PMID 40427500, 2025). "In terms of the connection between LEP and LEPR gene variants and obesity, there is limited information regarding the presence of MetS." (PMID 39136228, 2025). "Adipose tissue in individuals with obesity secretes pro-inflammatory adipokines and cytokines, such as leptin, IL-1β, and IL-6." (PMID 40218960, 2025). "By contrast, down-regulation of GIP and resistin and leptin had been reported to be beneficial for obesity or diabetes treatment." (PMID 41356823, 2025). "In this mini-review we provide a brief overview of the monogenic mouse models of obesity that have led to the discovery of important physiological systems that regulate energy homeostasis, such as the leptin-melanocortin pathway, that translate well to humans." (PMID 40702736, 2025). "Obesity leads to the development of leptin resistance, which is marked by high levels of leptin in the bloodstream and a decreased responsiveness to its signals." (PMID 39931847, 2025). "Elevated leptin levels in HFpEF patients are largely attributable to higher body mass index, as obesity is both a driver of HFpEF pathogenesis and a key factor in increased leptin production." (PMID 40149908, 2025). "In this study, therefore, we aimed to utilize univariable, multivariable and bidirectional MR to examine the causal relationship between obesity (BMI, BFP, WHR), lipids (HDL, LDL, TG) and adipokines (LEP, ADPN, AgRP) with cognitive ability." (PMID 39996061, 2025). "The increased TRH and TSH in OSAHS with obesity are most likely due to the increased circulating leptin." (PMID 40438137, 2025).